IL6 (interleukin 6)
Diseases named in the same sentence as IL6 in open-access papers (continued):
Sharing a sentence is not in itself a finding about the gene and the disease.
tumor (continued). "IL-6 is considered one of the important cytokines in MDSC infiltration and regulation, as indicated in a study that showed that IL-6 inhibition in tumor-bearing mice depletes MDSCs and increases IFN-γ production by CD4+ and CD8+ T cells." (PMID 34163519, 2021). "IL6 enhanced lung colonization of OS cells by overexpression of ICAM-1 and promoted tumor metastasis." (PMID 33436536, 2021). "Qing-Re-Huo-Xue (QRHX) formulae increases the expression of iNOS and decreases the expression of IL-6, TNF-α, and Arg-1 through the JAK2/STAT3 pathway, further reducing the numbers of TAMs and inhibiting tumor growth in lung cancer mouse model." (PMID 33748122, 2021). "Additionally, in the subgroup of patients treated with SBRT, both IL-6 and IL-8 were increased, suggesting that the effect of radiotherapy on tumor immunogenicity might be dependent on the dose per fraction, but due to the small sample size, these results are not easy to interpret." (PMID 34830880, 2021). "Our results suggest that Rab37/IL-6/PD-1 functions in the same axis and thus provide a rationale design using combined treatment of α-IL-6 and α-CTLA-4 to promote anti-tumor efficiency." (PMID 34093869, 2021). "Using pY705-STAT3 as readout of IL-6 signaling, KPC mice showed increased pY705-STAT3 in muscle and fat, while KPC IL6KO tumor–bearing mice showed only increased pY705-STAT3 in fat." (PMID 33851955, 2021). "On the other hand, pro-inflammatory cytokines released by immune effector cells, such as IFN-γ, IL-6, TNF-α, IL-1 and TGF-β, up-regulated IDO-1 on tumor cells, thus representing an immune escape mechanism." (PMID 33920505, 2021). "The impact of C-7 on the levels of various cytokines (IFNγ, TNF, IL-6, and IL-10) and the chemokine CXCL10 was assessed in 1-day co-culture supernatants of dissociated CRC tumor cells and autologous PBMC." (PMID 34771609, 2021). "They express low level of αSMA but high levels of cytokines and chemokines such as IL-6, IL-11 and leukemia inhibitory factor (LIF) and promote tumor growth." (PMID 34290984, 2021). "Tumour exosomal PGE2 and TGF-β strengthen the induction of MDSCs, activate the upregulation of Cox2, IL-6, VEGF, and ARG-1 in MDSCs, and promote T-exosome-mediated tumour proliferation." (PMID 34193120, 2021). "For this, M-MDSCs and G-MDSCs isolated from NB-tumor-bearing mice were stimulated with DMSO or ibrutinib for 1 h, followed by the addition of IL6 and GMCSF for 24 h and analysis of mRNA expression of Arg, Ido1, and Tgfβ by qRTPCR." (PMID 33669187, 2021). "SVF secretes the cytokine Interleukin-6 (IL-6) in a DDR1-dependent manner, and SVF produced IL-6 increases tumor cell invasion in vitro." (PMID 34805157, 2021). "IL-6 activates the signal transducer and activator of transcription-3 (STAT3) signaling pathway which in turn, acts to promote tumor growth and anti-tumoral immunity." (PMID 32797354, 2021). "Aberrant hyperactivation of IL‐6/STAT3 signaling occurs in many types of cancer and drives the proliferation, survival, invasiveness, and metastasis of tumor cells." (PMID 34375503, 2021). "We and others have found that BI-ALCL tumor cells exhibit an activated CD4+ transcriptional profile with T regulatory features due to an IL10-, IL6-, IL13- and Eotaxin-rich cytokine microenvironment." (PMID 34944796, 2021). "We know that MSCs are highly prone to tumour stroma and can promote MDR by increasing the expression of multi-drug resistance genes or by paracrine pathways (STAT3, IL-6, IL-8, etc.)." (PMID 33541299, 2021). "In cytokine and chemokine array analyses the overexpression of Lrp5 reduced the levels of several tumor-promoting factors in CM, including CXCL2, GM-CSF, IL6, LIF, DLK1 and MRP with an increase in IL27, a tumor-suppressing cytokine." (PMID 33859739, 2021). "IL-6 binds with the IL-6 receptor which activates signal transducer and activator of transcription 3 (STAT3) pathways that drive tumor cell proliferation, EMT, migration, invasion, and metastasis." (PMID 34220337, 2021).
tumor (continued). "In the current study, tumor concentrations of TNF-alpha, IL-6, IL1-beta and MCP-1 were positively correlated with a higher OSCC volume." (PMID 33411841, 2021). "IL-6 is shown to have a key function in SCC progression by regulating a complex network of cytokines and proteases, and the tumor invasion induced by it is supported by MMP-1 overexpression." (PMID 33917793, 2021). "We detected the early production of several inflammatory cytokines in the CD4+ T cells of tumor-bearing STAT1-/- iso mice, with higher levels of IFN-γ, IL-6, and IL-17, compared with their WT counterparts." (PMID 34299314, 2021). "IL6 has already been shown to induce EMT and tumor progression, and we have demonstrated that MCPIP1 directly regulates the levels of IL-6 in ccRCC in vitro and in vivo." (PMID 34657130, 2021). "Similar to IL-6, the correlation between TNF and tumor grade, size, metastases, or recurrence was investigated." (PMID 34359785, 2021). "RT-qPCR analysis in the present study revealed that Rh2 regulated the expression levels of IL-1, IL-6, IL-10 and TNF-α, which inhibited tumor invasion and angiogenesis." (PMID 34452568, 2021). "Further, we observed inhibition in the level of TGF-β in the ascitic fluid of MJ-administered tumor-transplanted mice, along with an increase in the level of IFN-Ƴ and IL-6." (PMID 33718176, 2021). "Agrin enhanced tumor growth and invasion through PI3K/AKT pathway, and induced IL-6 expression and secretion in NSCLC cells to promote Treg differentiation." (PMID 35111682, 2021). "Recent studies have shown that neutrophils can produce and release active cellular factors, such as IL6-1, IL-6 and VEGF, which changes the balance of inflammatory and anti-inflammatory in the tumor microenvironment." (PMID 33752642, 2021). "These include IL-6, IL-8 and TNF-α as well as the immune suppressive cytokines IL-10 and TGF-β, which increase HLA-G expression on tumor cells resulting in promotion of evasion from immune cells." (PMID 35111159, 2021). "In concert with IL-6, CCL2 increases the survival of macrophages and stimulates their differentiation towards a tumor-promoting M2-like phenotype." (PMID 34064859, 2021). "Our previous reports demonstrated that IL-6, CCL2, and PAI-1 derived from CAF-like cells also have tumor-promoting roles, including the induction of migration and invasiveness of ESCC cell lines." (PMID 34572779, 2021). "The overexpression of the inflammatory cytokines, IL-6 and TNF have been reported in the tumour microenvironment, where they promote all the hallmarks of cancer, including cell proliferation, angiogenesis, invasiveness, and metastasis." (PMID 34064686, 2021). "In murine models, depletion of macrophages/microglia has led to a reduction in tumor growth and in line with this, some factors released by GAMs such as IL-6, IL-1β, EGF, STI-1 and TGF- β can promote tumor growth." (PMID 33802571, 2021). "Additionally, the HIFU-induced upregulation of the genes Il6 and Il1β, which the authors hypothesized could promote a chronic inflammatory pro-tumor environment, was attenuated and the tumor infiltration by dendritic cells was enhanced with the addition of immunotherapy." (PMID 34063752, 2021). "Of those patients with a low IL-6 who died, or developed recurrent RCC disease (n = 10) only one had a RCC tumor with a diameter < 7 cm at diagnosis." (PMID 32621022, 2021). "Beyond that, TAMs can produce matrix metalloproteases (e.g., MMP2 and MMP9) and factors (e.g., TGF-β, PDGF, IL-6, urokinase plasminogen activator (u-PA), and tissue-type plasminogen activator (t-PA)) to degrade the ECM for tumor invasion and migration." (PMID 34138315, 2021). "Overproduction of IL-6 by tumor cells activates STAT-3, a key transcription factor central to immune escape and it is an important regulator in the crosstalk between tumor cells and TME." (PMID 35059436, 2021).
tumor (continued). "We observed significant changes in tumorigenesis-related markers including CD133, Bmi-1, VEGF, MMP-3, IL-1β, IL-6, TNF-α, and MDR in the tumor group compared with the control group." (PMID 34527741, 2021). "According to a previous report, we transplanted Lin-CD34+ UCB cells into human IL-6-Tg NOG mice, which generates TAMs with a functionally immunosuppressive nature and show an enhanced tumor-growth." (PMID 33692791, 2021). "Furthermore, exposure to IL-6 enhanced pericyte immunoregulatory function, suggesting that tumor-derived factors may convert pericytes to a form that instructs the immune system in a manner beneficial to the tumor." (PMID 34497540, 2021). "Cell signaling pathways and secretory factors including TGF-β, IGF-1, Notch, IL6, CXCR4, and PTHrP contribute to tumor growth in the bone microenvironment." (PMID 34503118, 2021). "IL6 levels were significantly elevated in young C26 tumor bearing mice, whereas young LLC tumor bearing mice had unaltered IL6 levels." (PMID 35008253, 2021). "For instance, CAFs secrete growth factors such as CXCL12, HGF, EGF, IGF, IL‐6, IL‐8, IL‐11 and CCL5, which facilitate tumour growth." (PMID 33943003, 2021). "Some of these changes are beneficial when it comes to non-tumor-promoting conditions, e.g., the decrease of VEGF, TGFβ, IL6, CXCL1, CXCL9, IL1β, and M2-macrophage-inducing IL4, as well as the increase of immuno-supportive and M1-associated IL12p70 and TNFα." (PMID 34064000, 2021). "Senescent cells, after genotoxic stress, secrete IL6 and IL8 that promote epithelial-mesenchymal transition, increasing tumor cells’ invasiveness." (PMID 34447383, 2021). "Myeloid differentiation and MDSC expansion are promoted by a variety of molecules, such as GM-CSF, M-CSF, IL-3, IL-6 and VEGF which are produced by tumor cells and the mechanisms used to recruit MDSCs in tumor-draining and distant LNs are described." (PMID 34241649, 2021). "For instance, some studies have shown that both IL6 and OSM are capable of inducing tumour-promoting effects through STAT3, while IL6, IL11, LIF and OSM can all promote invasion and metastasis through the JAK/STAT3 and PI3K/AKT pathways." (PMID 34834425, 2021). "In this study, the proinflammatory mediator S100A8/A9 in combination with species-specific expression of proinflammatory cytokines IL6 (mouse) and IL8 (human) established a pro-metastatic primary tumor niche in the Hltf-deleted TME." (PMID 34010296, 2021). "Finally, the IL‐6 levels were found slightly increased during exercise, which aligns with published data from mouse models, and may be related to NK cell re‐distribution to the tumor microenvironment." (PMID 34110712, 2021). "IL-6 is also a common cytokine that enhances TGF-β signaling, resulting in EMT, and stimulates tumor progression." (PMID 33807441, 2021). "Autocrine IL-6 further enhanced IL-10 and IL-21 production by CD4+T cells via STAT3, supporting tumor growth and metastasis." (PMID 34917098, 2021). "As far, the studies of cytokines that was from tumor microenvironment and induced EMT program, such as TGF-β, IL-6 and vascular epidermal growth factor, always addressed on CAFs." (PMID 33744858, 2021). "The contribution of autophagy to tumour progression was evident in grade III gliomas, in which IL-6, HIF1A (marker of hypoxia) and LC3B (marker of autophagy) were found to co-localise in hypoxic regions within the tumours." (PMID 33803414, 2021). "IL-6, a part of numerous biological factors, is released along with VEGF and Matrix Metalloproteinases (MMPs) by Toll-like Receptors (TLRs) when tumour cells dodge immune surveillance." (PMID 34336101, 2021). "Evidence suggests that the release of tumor-derived soluble mediators, such as GM-CSF, VEGF, or IL-6 impairs the myeloid compartment and thus contributes to defective myeloid cell maturation." (PMID 33430105, 2021).
tumor (continued). "TGF-β, IL-6, HIF1α, β-catenin, vimentin, casein kinase, and several EMT-inducer microRNAs (miRNAs) such as miR-301a-3p, miR-146a, miR-155, and miR-32-5p in tumor-derived exosomes are essential factors in the EMT mechanism." (PMID 34660694, 2021). "In the tumor microenvironment, IL‐6/JAK/STAT3 signaling acts to drive the proliferation, survival, invasiveness, and metastasis of tumor cells." (PMID 34026434, 2021). "Combinatorial induction of IL6 and S100A8/A9 in the Hltf-deleted TME with ICAM-1 and IL8 in the primary tumor activated a positive feedback loop." (PMID 34010296, 2021). "The reduction of tumour cell adhesion in the presence of neutralizing antibodies to MCP-1 and IL-6 supports the involvement of these molecules, either on endothelial or tumour cells, in tumour cell adhesion." (PMID 34223877, 2021). "These macrophages secrete proinflammatory factors such as IL-6, IL-12, IL-1β, and TNF-α and highly express MHC class I and MHC class II molecules that recognize tumor-specific antigens." (PMID 34335093, 2021). "First, we tested the therapeutic efficacy of co-administration of α-IL-6 and anti-CTLA-4 antibody (α-CTLA-4) on LLC tumor growth in subcutaneous model." (PMID 34093869, 2021). "During tumor development, TH17 promoting chemokines and cytokines are expressed within the TME, such as CCL4, CCL17, CCL22, IL-1β, IL-6, IL-23, and TGF-β." (PMID 34012451, 2021). "In BM+ tumor cells CCL20 exhibited a dramatic increase, while cytokines/chemokines such as CCL8, IL-6, and tumor necrosis factor superfamily members also showed an increasing trend." (PMID 34222020, 2021). "After 24-h co-incubation of tumor cells and effector T cells at an E:T ratio of 10:1, B7-H3 CAR-T cells produced significantly higher amounts of IFN-γ, TNF-α, IL-2, IL-6, IL-4 and IL-10 in the culture supernatants compared with vehicle T cells." (PMID 33514401, 2021). "Higher tumor levels of TNF-alpha, IL-6, IL1-beta and MCP-1 were positively correlated with OSCC growth." (PMID 33411841, 2021). "In the tumor microenvironment, hyperactivation of IL-6/JAK/STAT3 signaling pathway acts as a powerful suppressor of anti-tumor immune response and as a promotor of tumor progression, leading to a poor prognosis of cancer patients." (PMID 33854592, 2021). "Tumour-supporting cytokines and chemokines, such as TGF-β, IL-6 and MCP-1, are released from tumoural and stromal cells through AT1R activation by Ang II23,54." (PMID 34620946, 2021). "The NK-exosome-treated tumor group showed a meaningful reduction in the expression of Bmi-1, MMP-3, IL-1β, IL-6, TNF-α, Bax, and Bcl-xL compared with the tumor group." (PMID 34527741, 2021). "IL-6 expression is increased in CRC tissue and tumor stromal fibroblasts expressing CD90 are the major cell phenotype producing IL-6." (PMID 34681633, 2021). "IL-6 is generally known to be one of the major critical cytokines in the TME, promoting tumor proliferation and differentiation." (PMID 34439154, 2021). "Production of IL-6 by myofibroblasts isolated from CRC was also noted, in an amount higher compared to tumor-cell secretion, inducing angiogenesis via the up-regulation of VEGF-A." (PMID 33557173, 2021). "Cancer cell-, osteoblast-, or adipocyte-derived IL-6 and IL-8 directly or indirectly promote EMT, angiogenesis, tumor cell growth, migration, and metastasis, as well as CAFs activation by interacting with additional inflammatory pathways." (PMID 34064859, 2021). "Tumor cells directly stimulate osteoclastogenesis by expressing molecules such as RANKL, IL-6, IL-8, IL-11, IL-1, and IL-1B; they also indirectly stimulate osteoclastogenesis by increasing RANKL production in osteoblasts via PTHrP expression." (PMID 34257573, 2021).
tumor (continued). ", IL-6, M-CSF, PGE2, IL-10, and VEGF) on DCs would promote anti-tumor efficiency by recruiting and promoting the maturation of DCs." (PMID 34248142, 2021). "It has been observed that TAMs promote HCC development, and support the expansion of CSCs by IL-6 secretion, highlighting the complex interaction between the components of the TME to sustain tumor growth." (PMID 33737571, 2021). "The ligand IL-6 is also involved in the cross-talk between TAM and tumor cells and promotes the survival of tumor cells in hypoxic conditions and the differentiation of cancer stem cells." (PMID 33842333, 2021). "Treatment with transforming growth factor-β1 (TGF-β1), a major cytokine found in a tumour, significantly alters the MMP activity and IL-6 concentration." (PMID 33758206, 2021). "Infiltrating neutrophils continue to promote tumor development by secreting pro-inflammatory and pro-angiogenic chemokines and cytokines, such as matrix metallopeptidase 9 (MMP9) and interleukin 6 (IL-6)." (PMID 34503307, 2021). "Due to the secretion of IL6, IL8, SDF-1, TGF-β1, and other cellular factors, CAFs contribute to the development of an inflammatory tumor environment." (PMID 33782384, 2021). "PD-1 on TI DCs from human ovarian cancer patients and mouse tumor tissues suppresses cytokine production (TNF-α and IL-6) and costimulatory molecule expression (CD40 and CD80)." (PMID 34901012, 2021). "The overexpression of COX-2 in TAMs also up-regulates IL-6, which perpetuates high levels of COX-2 in tumor cells." (PMID 34178680, 2021). "One of the most important activators of the gp130-JAK-STAT3 pathway is IL-6, with STAT3 known to induce tumour growth and immunosuppression." (PMID 34944729, 2021). "For example, the overexpression of immune-effector cytokines such as IL-6 and PGE2 not only increase the tumor-infiltration of immune cells, but also induce stemness in the LUSC cells, thereby reducing their recognition by the immune surveillance machinery." (PMID 33428598, 2021). "The experiment determined the secretion levels of tumor TNF-α, IL-6, and IL-10 in RAW264.7 cells after treatment with different MP concentrations." (PMID 34436307, 2021). "Differential analysis of IL6, IL6R, and IL6ST revealed that these genes were significantly modulated in most of the selected TCGA tumor cohorts (n = 33) compared to normal tissues." (PMID 34576335, 2021). "There are also other reports indicating that neutrophil activation is promoted in gastric cancer by MSC-derived IL-6 through the STAT3-ERK1/2 signal transduction pathway and that their polarization is induced toward a tumor-supportive phenotype." (PMID 33472580, 2021). "To investigate the frequency with which tumors express IL-6 from malignant cells, we performed immunohistochemistry (IHC) on a PDAC tumor microarray." (PMID 33851955, 2021). "In colorectal cancer, tumor cells release IL-1, which induces MSCs to secrete PGE2 and raises IL-6 level, which leads to the development of CSCs." (PMID 34736460, 2021). "Of note, IL6, IGFBP3, and CXCL16 were identified as the tumor-derived factors responsible for the induction of CD38 expression in MSDC ex vivo." (PMID 33390169, 2021). "Likewise, when we explored the effects of IL1β-silenced tumor cells on co-cultured NCFs, we could observe that cocultured fibroblasts lost the expression of inflammatory cytokines, as IL6, LIF or CCL2, while acquired markers of myofibroblasts (ACTA2, PDPN, MYH11, or CNN1)." (PMID 34066976, 2021). "Interestingly, IL-6R neutralization negatively regulates angiogenesis and tumor growth through IL-6 signaling downregulation, supporting the hypothesis that considers IL-6 signaling proteins to be useful targets in CRC therapy and in several other human diseases." (PMID 33923292, 2021).